MYBPC2 (myosin binding protein C2)
Description:
Thick filament-associated protein located in the crossbridge region of vertebrate striated muscle a bands. In vitro it binds MHC, F-actin and native thin filaments, and modifies the activity of actin-activated myosin ATPase. It may modulate muscle contraction or may play a more structural role.
Synonyms: MYBPCF; MGC163408; fsMyBP-C; MYBPC
Tractability: PROTAC: ubiquitination databases record sites on it.
Gene: Protein-coding gene on chromosome 19 (50,432,805 to 50,466,328, forward strand). Ensembl gene ENSG00000086967.
Pathways (Reactome):
Muscle contraction: Striated Muscle Contraction
Gene Ontology:
Molecular function: protein binding; structural constituent of muscle
Biological process: sarcomere organization
Cellular component: cytosol; M band
Genetic constraint (gnomAD): Loss-of-function variants: 119 observed, 124.39 expected, observed/expected ratio (o/e) 0.96, 90% interval 0.82 to 1.11. The upper end of that interval is the gene's LOEUF score, 1.11, which puts it in group 4 of 6, group 1 being the genes least tolerant of losing a copy. Missense variants: 1,427 observed, 1,453.1 expected, observed/expected ratio (o/e) 0.98, 90% interval 0.94 to 1.03. Synonymous variants: 605 observed, 582.37 expected, observed/expected ratio (o/e) 1.04, 90% interval 0.97 to 1.11.
Homologues: Orthologues: chimpanzee MYBPC2 (97% identical), macaque MYBPC2 (96% identical), mouse Mybpc2 (92% identical), guinea pig MYBPC2 (91% identical), dog MYBPC2 (91% identical), pig MYBPC2 (90% identical), rat Mybpc2 (88% identical), tropical clawed frog XB5889096 (71% identical), zebrafish mybpc2b (60% identical), Caenorhabditis elegans C34F6.10 (16% identical), Drosophila melanogaster mtgo (12% identical). Paralogues in human: MYBPC3 (55% identical), MYBPC1 (50% identical), IGSF22 (27% identical), MYBPH (20% identical), MYOM1 (19% identical), OBSL1 (19% identical), MYOM2 (18% identical), MYOM3 (17% identical), FNDC3A (16% identical), FNDC3B (15% identical), MYBPHL (15% identical).
Diseases named in the same sentence as MYBPC2 in open-access papers:
MYBPC2 is named in the same sentence as 16 diseases in open-access papers, as found by Europe PMC text mining. Sharing a sentence is not in itself a finding about the gene and the disease. The quoted sentences say what the papers report.
skeletal myopathies (2 papers, 2022 to 2023). "Studies have shown that lack of Mybpc2 expression can lead to severe skeletal myopathy, increased apoptosis, up-regulated expression of factors related to muscle protein degradation, accompanied by structural changes and muscle weakness." (PMID 37070092, 2023). "Mutations in the MYBPC family of genes, including slow skeletal (MYBPC1), fast skeletal (MYBPC2) and cardiac (MYBPC3), can result in cardiac and skeletal myopathies." (PMID 35832193, 2022).
breast carcinoma (1 paper, 2019). "Moreover, we are the first to report the prognostic value of MYBPC2, FAM159A, and FAM179A in breast cancer, which may provide novel directions for further investigation." (PMID 32047513, 2019).
cardiac hypertrophy (1 paper, 2015). "Similarly regulated transcripts between previous studies utilizing TAC-induced cardiac hypertrophy and this study include Acta1, MybpC2/3, Actn2, and Myh7 among others indicating an appropriate hypertrophic gene transcriptional response in WT mice." (PMID 26192751, 2015).
diabetic cardiomyopathy (1 paper, 2025). Diabetic cardiomyopathy is a disorder of the heart muscle in people with diabetes. "Sciatic nerve proteomics showed a significant increase in LRP group myosin, TNN13, MYL7, MYL3, TNNC, MYBPC2, ACTN2, and KEGG enrichment analyses showed that these proteins were mainly enriched in pathways such as cardiac contraction, diabetic cardiomyopathy, and dilated heart disease." (PMID 40321612, 2025).
dilated cardiomyopathy (1 paper, 2024). Cardiomyopathy which is characterized by dilation and contractile dysfunction of the left and right ventricles. "Hypertrophic and dilated cardiomyopathy causing mutations have been detected mostly in genes of sarcomere proteins such as Mybpc2, Myh7, Tnnt2, Tnnc1, Tnni3, Tpm1, Ttn, Actc1, Myl2, and Myl3." (PMID 38981849, 2024).
hypertrophic cardiomyopathy (1 paper, 2015). A condition in which the myocardium is hypertrophied without an obvious cause. "Furthermore, using a single gene model, Meurs & Kuan evaluated the methylation of the CpGs within the exon regions of the skeletal muscle isoform of the myosin binding protein C gene (MYBPC2) and cardiac myosin binding protein C gene (MYBPC3), a common causal gene for hypertrophic cardiomyopathy." (PMID 26701604, 2015).
renal fibrosis (1 paper, 2016). A final common manifestation of a wide variety of chronic kidney diseases characterized by glomerulosclerosis and tubulointerstitial fibrosis. "The list of genes includes Fblim1, Epha2, Wisp1, Parvg, Madcam1, Mybpc2, Cdh3, Gpr56, Troap, Pstpip1, Pcdh8, Nlgn2 and Mfap4, genes that based on Pubmed and Kidney and Urinary Pathway Knowledge Base12 searches have not been previously associated with renal fibrosis." (PMID 27189340, 2016).
type 2 diabetes (1 paper, 2025). "Importantly, a large number of sarcomeric proteins (such as myosin light chain kinase 2 [MYLK2], MYBPC2 and myosin light chain 4 [MYL4]) were downregulated in type 2 diabetes muscle fibres." (PMID 40295335, 2025).
tumor (5 papers, 2006 to 2025). "Down-regulated genes in the irradiated tumor in significantly enriched GO categories related to smooth muscle and pericytes such as Des, Myh4, Ttn and Mybpc2." (PMID 22927920, 2012). "The transitional CpGs of the MYBPC2 gene bordered by the high-density Alus were hypermethylated at a level ≥ 3 in the normal tissues but were unchanged in the tumor tissues." (PMID 16827945, 2006). "MYBPC2, TMEM109, and LACM3 have also been associated with various tumor types." (PMID 41009814, 2025).
inflammatory myopathies (2 papers, 2018 to 2020). "Mutations and abnormal expression of MYBPC2 or LDB3 have been associated with myopathies and cardiopathies, which indicates that cytoskeletal proteins participate in the formation of pathological changes in FHL1 KO mice." (PMID 30083183, 2018).
cancer (1 paper, 2024). A tumor composed of atypical neoplastic, often pleomorphic cells that invade other tissues. "Regarding the remaining DEPs, Myh4, Acta1, Tnnt3, Mb, Ttn, Actn2, Myh7, Myl1, Mybpc2, Myl3, and Tnnc2 are associated with several cancers." (PMID 39861068, 2024).
infection (1 paper, 2022). The state of being infected such as from the introduction of a foreign agent such as serum, vaccine, antigenic substance or organism. "Only a single gene, encoding myosin-binding protein C2 (Mybpc2), is shared between comparisons 1 and 2, highlighting that it is less abundant with STAg treatment with or without infection." (PMID 34928716, 2022).
MYBPC2 also shares sentences with these, for which no sentence is quoted: arthrogryposis (1 paper); diabetic retinopathy (1); Insulin resistance (1); myositis (1).